MSH6 (mutS homolog 6)
Diseases named in the same sentence as MSH6 in open-access papers (continued):
Sharing a sentence is not in itself a finding about the gene and the disease.
uveal melanoma (1 paper, 2021). A melanoma derived from melanocytes of the uveal tract. "In addition, DFS (Disease-free survival) analysis showed that high expression of MSH6 was correlated to poor prognosis for cancers of KIRP (P=0.038), ACC (P=0.00015), UVM (Uveal melanoma) (P=0.038) and LGG (P=0.045)." (PMID 34941572, 2021).
villous adenoma (1 paper, 2025). An epithelial neoplasm morphologically characterized by the presence of a villous architectural pattern.
tumor (626 papers, 2001 to 2026). "In particular, the use of panels of mononucleotide repeat MSI markers is recommended to enhance MSI detection in MSH6-deficient tumours, in agreement with the recent ESMO guidelines." (PMID 40836023, 2026). "While the IHC pattern supports loss of MLH1 expression, the tumor also harbors a pathogenic MSH6 variant at a variant allele frequency of 46%." (PMID 41347766, 2026). "Tumor sequencing confirmed both germline variants but showed microsatellite stability and no loss of heterozygosity, arguing against a causal role of MSH6." (PMID 41919251, 2026). ": A sixteen-year-old patient diagnosed with left-sided metastatic mucinous colon cancer carrying a pathogenic MSH6 gene variant (c.3416delG) and exhibiting a tumour mutation burden of 151.4 mutations/Mb." (PMID 40133691, 2025). "In contrast, it has previously been observed in several studies that MSH6 deficient tumours have lower MSI than other MMRd tumours or are microsatellite stable." (PMID 40651337, 2025). "The high mutant allele frequency of MSH6 (73%) suggested a potential germline mutation, considering the estimated tumor cell content of 46.4–50%." (PMID 40530006, 2025). "The proband with the MSH6 gene variant was older and had a tumor recurrence, which is consistent with the results of previous reports." (PMID 38280988, 2024). "Remarkably, within larger MSH6-deficient tumor clones, we frequently found numerous nested subclones with intact MSH6 expression." (PMID 38956208, 2024). "Using LCM and whole-exome sequencing, we can directly assess mutation burden within individual MSH6-proficient and deficient tumor subclones and reconstruct highly resolved phylogenetic trees." (PMID 38956208, 2024). "We developed a dedicated FluORescence cell segmentatION (ORION) workflow based on ellipsoidal modeling to accurately quantify immune cell infiltration both within and between MSH6-proficient and MSH6-deficient tumor regions." (PMID 38956208, 2024). "WES after LCM confirmed that tumor regions carrying frameshift mutations in either the MSH6 or MSH3 homopolymer had significantly increased SNV, InDel and overall mutation burden." (PMID 38956208, 2024). "The reduction in MSI signal we observed in ECs with isolated MSH6 loss adds to a growing body of evidence that the detection of such tumours is particularly challenging using MSI." (PMID 39682157, 2024).
tumor (continued). "We also investigated the role of MSH3 Ala1045Thr and MSH6 557G > T polymorphism based on clinical-pathological features such as stage, tumour size, lymph node invasion and metastasis." (PMID 39003369, 2024). "There was disagreement between the MSI assays in three cases, and both classified five out of the eight tumours with isolated MSH6 loss as MSS." (PMID 39682157, 2024). "Colabeling for MSH6 and a pan-cytokeratin (pan-CK) epithelial marker showed scattered epithelial tumor ribbons and single tumor cells with intact MSH6 labeling within MSH6-deficient tumor regions (insets ii and iii)." (PMID 38956208, 2024). "The impact of the MSH3 Ala1045Thr and MSH6 557G > T variants on various clinicopathological parameters, such as stage, tumor extension, lymph node invasion, and metastasis, was assessed." (PMID 39003369, 2024). "To exclude the influence of MSH6 mutations, we performed the previous analyses on the MSH6 wild-type tumor samples and obtained consistent results." (PMID 38390329, 2024). "No tumors had a likely pathogenic mutation involving the HRD pathway; 1 tumor had a pathogenic mutation in MSH6, part of the mismatch repair (MMR) pathway." (PMID 36672477, 2023). "Multigene panel sequencing of tumor and blood-derived DNA identified an MSH6 somatic mutation (MSH6:c.1135_1139del p.Arg379*) common to both the EC and CRC, raising suspicion of mosaicism." (PMID 37318702, 2023). "Tumour samples with high mutation burden and with mutations in mismatch repair genes were dominated by various microbiota and metabolome clusters, although MSH6 gene mutations were present only in tumour samples in which metabolome cluster 1 was dominant." (PMID 37158960, 2023). "LGG has been linked to a greater risk of tumor recurrence and a poorer prognosis resulting from mutations in MSH6." (PMID 37660060, 2023). "The tumor showed a somatic MSH6 mutation (MSH6 c.3261del p.Phe1088Serfs*2) and was positive for MLH1 methylation accounting for the loss of MLH1/PMS2." (PMID 37101184, 2023). "The histopathological work-up showed necrosis in former tumor lesions and one vital adenocarcinoma of the small intestine, again with an immunohistochemical-confirmed loss of MSH6 expression." (PMID 37569431, 2023). "High MSH6 further associated with the TCGA molecular subgroup of copy number high tumours (P < 0.001) and predicted reduced survival with a 5-year DSS of 84% in the high expression group and 94% in the low expression group (P < 0.001)." (PMID 36482191, 2023).
tumor (continued). "The one tumor with retained MMR protein expression that was MSI-H was from a carrier with a missense MSH6 variant (c.3259C>T), which showed loss of MSH6 protein expression in 70% of the tumor cells." (PMID 37143941, 2023). "We observed pathogenic indels in MSH6 in all seven tumours, but only one of these in mono- or dinucleotide repeat DNA." (PMID 36883553, 2023). "The other FDR belonged to a family with a truncating MSH6 variant, and the tumor showed loss of expression of MSH6." (PMID 37143941, 2023). "By contrast, the wild-type MSH6 allele was retained in the tumor and the variant MSH6 c.3936_4001+8dup allele was reduced." (PMID 36612224, 2022). "The 557 PDO line contained a MSH6 frameshift mutation (F1104fs), and the parent tumour also displayed deficient mismatch repair (dMMR) phenotype on immunohistochemistry." (PMID 35860583, 2022). "This is because Case 3 tumor cells have high mutation burden due to frameshift mutation in MSH6, and when the existing criteria are adapted, there are too many candidate neoantigens." (PMID 35228610, 2022). "MSH6 gene was mutated within a tumor that originated within the white matter of the parietal lobe with highest gene expression of being seen in corpus callosum, cingulum bundle, and thalamus." (PMID 34257334, 2021). "In agreement, a pan-cancer analysis of MSI found that 78.4% (29/37) of LS-associated microsatellite stable tumours were from carriers of either MSH6 or PMS2 pathogenic variants." (PMID 33499123, 2021). "Analysis of the two brothers’ tumor brain tissues confirmed that both were compound heterozygous MSH6 c.3261dupC and c.762dupT mutation carriers." (PMID 33924881, 2021). "In contrast, we found that PD-L1 was expressed by the tumor cells of only three out of 19 tumors with solitary MSH6 loss." (PMID 34685418, 2021).
tumor (continued). "For case number 17, paraffin blocks were available, and the tumor showed a tumor cell specific loss of MSH6 expression." (PMID 33216206, 2021). "One of these hypermutated tumours with a mutation burden of 14.97 mutations/Mb was from case 3 with a pathogenic germline MSH6 variant." (PMID 37435187, 2021). "Loss of MSH6 results in a deficiency in mismatch repair which can increase neoantigen presentation on tumour cells and promote T-cell infiltration." (PMID 33479301, 2021). "Two patients harboured MSH6 missense mutations, and immunohistochemistry (IHC) of the tumour tissue of one patient revealed abnormal staining because of heterogeneous patterns of MSH6 loss, which implies differences in mismatch repair (MMR) status." (PMID 33574476, 2021). "Indirect support for true MMR deficiency in the identified MSS tumor with MSH6 protein loss comes from its strikingly high density of intratumoral CD8 positive lymphocytes (958 cells/mm2)." (PMID 32108923, 2020). "Next generation sequencing of tumor tissue revealed mutations in MSH6 and MLH1, in addition to high microsatellite instability." (PMID 33292409, 2020). "Case 50N/T had possible pathogenic mutation (c.3438+1G>A) in MSH6 gene with increased disease risk in both normal tissue and tumor tissue." (PMID 31983041, 2020). "Given the unusual recurrence of cSCC in a new location and the presence of MLH1 and MSH6 mutations in the tumor with an unclear family history of cancer, germline genetic testing for hereditary cancers was performed after discussion with the patient." (PMID 33292409, 2020). "Next Generation Sequencing (NGS) analysis identified PMS2 mutations (germline in one tumour and somatic in the other) as the primary event and somatic MSH6 mutation as the secondary event in both tumours." (PMID 32664968, 2020). "NGS analysis of these tumours identified PMS2 mutations (R134* germline mutation in one tumour and M1R and c.1239delA somatic mutation in the other) as the primary event and somatic MSH6 mutation (c.3261dupC) as the secondary event in both tumours." (PMID 32664968, 2020). "MSH6, one of DNA mismatch repair genes, is overexpressed in PCa and is linked to genetic instability and tumor aggressiveness." (PMID 33014785, 2020). "It is of note that the tumor with an isolated but clear-cut loss of MSH6 expression was microsatellite stable in our PCR analysis." (PMID 32108923, 2020). "By CCP screen, the tumor of F70 II.5 revealed a nonsense mutation in MSH6: c.2932C>T, p.(Gln978Ter), VAF 22%, serving as a likely “second hit”." (PMID 32660107, 2020). "The sequence results for case 50N/T indicated possible pathogenic mutations in the MSH6 gene in both tumor and normal tissue, which supported the MSI-H results shown from MSI testing." (PMID 31983041, 2020). "No obvious second hit (somatic mutation or loss of heterozygosity (LOH)) in MSH6 was detectable in the patient’s tumor tissue." (PMID 32660107, 2020).